CTLA4 (cytotoxic T-lymphocyte associated protein 4)
Diseases named in the same sentence as CTLA4 in open-access papers (continued):
Sharing a sentence is not in itself a finding about the gene and the disease.
tumor (continued). "For all further analyses, the average densities of CTLA-4+ cells obtained by both antibodies were used for each patient except for tumor samples with >5% of non-specific staining." (PMID 35091676, 2022). "In addition, we found that TCF1−Texterm expressed higher levels of TIM-3, CTLA-4, and TIGIT, which are markers of a dysfunctional subset of tumor-infiltrating CD8+PD1+ T cells in cancer." (PMID 35153298, 2022). "FNDC3B expression was positively correlated to the tumor-infiltrating lymphocytes and immune infiltration score, and high FNDC3B expression was accompanied by the increased expression of B7-H3, PD-L1, TIM-3, PD-1, and CTLA-4." (PMID 36275754, 2022). "Hence, CTLA4-specific antibodies mainly act within the lymph nodes, while PD1- and PDL1-specific ICI act within the tumor microenvironment during a later stage of T cell activation." (PMID 36303101, 2022). "In addition, several other approaches developed CRISPR/Cas9-mediated PD1-disrupted CAR-T cells and CTLA-4–specific CAR-T cells to improve effector function of CAR-T cells and enhance their anti-tumor activity." (PMID 35720364, 2022). "Studies on less common tumor entities and larger patient cohorts require the use of routinely processed formalin fixed tissues but were so far hindered by a relative lack of CTLA-4 antibodies suitable for immunohistochemistry (IHC)." (PMID 35091676, 2022). "Furthermore, a combination of anti-CTLA-4 and anti-PD-1 antibodies with the pan-HDACI belinostat potentiated the efficacy of these antibodies via upgrading the immune function and reducing tumor volume in a murine hepatocellular carcinoma model." (PMID 35897717, 2022). "Using the NXS2 model, it was observed that combining CPM with either anti-CTLA-4 or anti-4-1BB mAb did not result in any significant changes in either tumor growth or survival over CPM alone." (PMID 36097618, 2022). "In conclusion, a novel peptide LC4 targeting CTLA-4 was identified by phage display bio-panning, which has specific affinity with CTLA-4 and blocks the interaction between CTLA-4 and its CD80 ligand, which inhibits tumour growth." (PMID 36195696, 2022). "Indeed, when CTLA‐4 and PD‐1 ICI in combination are also added to the co‐cultures, strong IFNγ production, potentiated γδ T cell infiltrate and immune‐mediated tumor killing are detected." (PMID 35696610, 2022). "This is consistent with the development of tumor-specific immunologic memory following PIC + RT + anti-CTLA-4 treatment and demonstrates the achievement of an enhanced in situ vaccine effect in these mice compared to that achieved with RT + anti-CTLA-4." (PMID 35999216, 2022). "Additionally, CTLA4(apt)-STAT3 siRNA demonstrated a substantial inhibiting impact on tumor development and metastasis in a variety of mouse tumor models." (PMID 35890239, 2022). "In addition, VEGF can cause upregulation in the expression levels of the inhibitory receptors, such as TIM-3, CTLA-4, PD-1, and LAG-3 on T cells and on the expression levels of PD-L1 on tumor cells and MDSCs." (PMID 35037899, 2022). "Finally, in the future, in order to better study the tumor microenvironment, other lymphocyte subpopulations (PD1, PD-L1, CTLA4, etc.)also need to be taken into account, to identify personalized approaches that are not only diagnostic but also therapeutic." (PMID 36010863, 2022). "CTLA-4 and PD-1 in the tumor microenvironment act as negative regulators of immune activation, preventing anticancer immune response." (PMID 36569674, 2022). "In an orthotopic model of renal cell carcinoma, diet-induced obese (DIO) mice showed no therapeutic anti-tumour response to anti-CTLA-4 therapy." (PMID 35860241, 2022). "We found the combination of the components with RT and anti-CTLA-4 conferred inferior anti-tumor efficacy, with no mice rendered disease-free at day 60 post-treatment." (PMID 35999216, 2022).
tumor (continued). "CTLA-4 agonists have the ability to lower CTLA-4 binding to B7 and weaken the B7-1 and B7-2/CTLA-4 suppression systems that allows T cells to perform their anti-tumor functions more effectively." (PMID 35744922, 2022). "The promise of immunotherapy is particularly evident in the recent success of antibodies targeting cytotoxic T-lymphocyte antigen 4 (CTLA-4) and programmed cell death protein 1 (PD1)/PD-L1 immune checkpoints in promoting anti-tumor immune responses and extending survival in a number of cancer types." (PMID 35720289, 2022). "Thus, Treg cells inhibit the activity of migrating immune cells to the tumor environment by secreting inhibitory cytokines (TGF, IL-10) and expressing inhibitory molecules (CTLA-4)." (PMID 35954362, 2022). "We were curious to find out whether the immune checkpoints PD-1, CTLA-4, Tim3 and NKG2A were being expressed by tumour infiltrating lymphocytes (TIL) present in TME." (PMID 36185249, 2022). "Notably, the targets of most of the current immuno-oncology agents, such as PD-L1, CTLA-4, LAG-3 and TIM-3, express on the cell surface and can directly mediate tumor-immune interactions." (PMID 34980132, 2022). "In the case of anti-CTLA-4, the Fc tail was shown to have a critical role in promoting antibody-mediated cellular cytotoxicity (ADCC) leading to an increased CD8+ to Treg ratio, which promoted tumour rejection." (PMID 35123267, 2022). "Indeed, high CAPZA1 and AC026356.1 expression was significantly positively correlated with PD1, PD-L1, and CTLA-4 in LUAD, respectively, demonstrating that CAPZA1 can mediate tumorigenesis and progression by regulating tumor immune escape in LUAD." (PMID 36686785, 2022). "Monotherapy with anti-CTLA-4 or anti-PD-1 in clinical trials did not improve tumor growth in most cases." (PMID 35015785, 2022). "Whereas anti-CTLA-4 treatment successfully reduced tumor growth in MC38-Control tumors, it did not significantly reduce the growth of MC38-B7x tumors, demonstrating a phenotype of resistance to anti-CTLA-4 treatment in B7x-expressing tumors." (PMID 35523809, 2022). "Expression levels of immune checkpoint proteins such as PD-1, CTLA-4, TIM-3 and TIGIT, and checkpoint ligands including PD-L1 and galectin-9 are higher in peripheral blood or tumor tissue for CRC patients, compared with blood or colon tissue from healthy donors." (PMID 35874729, 2022). "T25 exhibited increased expression of PD-1, CTLA4 and low expression of CCR7, CD45RA, CD127 and CD28, consistent with previous studies that a subset of tumor-reactive CD8+ TILs were positive for CD103 and CD39 and exhibited an exhausted tissue-resident memory phenotype." (PMID 36311750, 2022). "The tumor cells were positive in 10 (18%, PD-L1), 0 (0%, PD-1), 18 (32%, CTLA-4), and 13 (23%, IDO) cases while the infiltrating lymphoid cells were positive in 10 (18%, PD-L1), 23 (40%, PD-1), 18 (32%, CTLA-4), and 13 (23%, IDO) cases." (PMID 36104728, 2022). "Inspiringly, several recent studies in murine tumor models have shown that a high dose of vitamin C synergized with ICIs therapy (anti-PD-1 with or without anti-CTLA-4) in several tumor types." (PMID 35330159, 2022). "Consistent with the gene expression profile of tumor antigen-specific CD8+ T lymphocytes in human tumors, the majority of all CD8+ subsets displayed an exhausted profile with expression of Tox, Pdcd1, CTLA4, Lag3, and Havcr2." (PMID 35260537, 2022). "Compared to tumors treated with combination therapy, the addition of physical activity inhibited the infiltration of immunosuppressive Treg cells and the expression of several immune checkpoints, including CTLA4, TIGIT and TIM3, reprogramming the tumor immune microenvironment." (PMID 35379324, 2022). "We analyzed the correlation between CLDN18.2 and other immune checkpoint inhibitors in the tumor core; unfortunately, we did not observe any correlation with PD-1, PD-L1, CTLA-4, LAG-3, or TIM-3." (PMID 35811317, 2022).
tumor (continued). "The tumor rejection rates were 20% in the age-matched control, 60% in mice previously treated with vehicle plus anti–CTLA-4, and 100% in mice previously treated with 7HP349 plus anti–CTLA-4." (PMID 35552271, 2022). "By inhibiting the interaction between the immune checkpoints expressed on T cells, such as PD-1 and CTLA-4 and their ligands (PD-L1 and CD80/86) expressed by tumor cells/antigen-presenting cells, ICIs induce the activation of T effector cells targeting tumor cells." (PMID 35372076, 2022). "When CTLA-4 binds to B7, T cells exhibit anergy during the negative regulation of anti-tumor immunity." (PMID 36119033, 2022). "In actual tumor therapy, the single immune function of CD8+ cells is not enough to destroy tumor cells, as the immune checkpoint inhibitors (anti-PD-1, anti-CTLA-4) are only 30% effective." (PMID 36531226, 2022). "Effector genes such as GZMB, GZMH and KLRG1 were the marker genes in clonotypes shared by all tissues, while the clonotypes present only in tumor showed upregulated T-cell exhaustion genes (HAVCR2, LAG3, CTLA4, TIGIT, PDCD1, and ICOS) and activation genes (SELL and TNFRSF9)." (PMID 36185254, 2022). "The tumor cells stimulated the proliferation of 15×19 CAR T cells, up-regulate the expression of activators (CD25 and HLA-DR), and down-regulation the expression of suppressors (CTLA-4 and PD1)." (PMID 36618357, 2022). "Interestingly, after PD-L1/CTLA-4 treatment, CTSO, MMP1, SPP1, and TPX2 were significantly up-regulated in tumor cells." (PMID 36225568, 2022). "The function of co-inhibitory receptors, including Tim-3, programmed death-1 (PD-1), cytotoxic T lymphocyte antigen-4 (CTLA-4), and lymphocyte-activation gene 3 (LAG-3), are critical for lymphocyte homeostasis prompting it a novel target for treatment in tumor and infection." (PMID 35250975, 2022). "TNF-α diffuses from the tumor to the pituitary gland; an additional source of TNF-α originates in the pituitary gland as ipilimumab (which is infused into the blood) and targets the CTLA-4 expressed on pituitary cells." (PMID 36355837, 2022). "In sample TJH08, the tumor areas commonly expressed high IDO1, low PD‐L1, and very low CTLA4." (PMID 35986392, 2022). "This was important for the therapeutic efficacy of ICB as,in contrast to parental KPAR tumours, anti-CTLA-4 failed to result in long-termdurable regression of Emv2-/- KPAR subcutaneoustumours." (PMID 35930804, 2022). "Cancer immunotherapy requires ICB, such as CTLA-4 and monoclonal antibodies against PD-1 or PD-L1, which restore the function of cytotoxic effector CD8+ T cells and kill cancer cells, leading to tumor suppression and a paradigm shift in cancer treatment for many cancer types." (PMID 36123348, 2022). "However, except for expression of PD-1 by CD45− cells in the contralateral (untreated) tumor, GSNO administered i.t. appeared to exert negligible effects on expression of tumor immunogenicity markers including calreticulin (CRT), CTLA-4, PD-1, and PD-L1." (PMID 35304456, 2022). "Blocking the negative T cell regulator CTLA4 reactivates immune response against the tumor in immunogenic cancers." (PMID 36578079, 2022). "In addition to the classical immune checkpoint molecules PD-1 and CTLA-4, T cell immunoglobulin mucin receptor 3 (TIM3, or HAVCR2) and LAG-3 are also included in the field of tumor immunotherapy research." (PMID 35601491, 2022). "Moreover, the frequency of CD3+CTLA-4+ cells and CD8+PD-L2+ cells positively correlated with more advanced stage tumours (p = 0.02 and p = 0.04)." (PMID 35366537, 2022). "To assess whether the sensitivity to ICB was dependent on theanatomic site of tumour growth, as previously shown, we also treated orthotopic KPAR lung tumours withanti-PD-1, anti-CTLA-4 or a combination of both." (PMID 35930804, 2022).
tumor (continued). "A high abundance of tumor infiltrating T cells is a predictive marker of ICI efficacy, and a low number of MDSCs has been shown to correlate with an increased chance of responding to anti-CTLA4 therapy." (PMID 35017664, 2022). "In contrast, quantitative IHC analysis of tumor tissues from cancer patients shows that anti-CTLA-4 immunotherapy using ipilimumab or tremelimumab (anti-human CTLA-4 hIgG2) did not deplete Foxp3+cells in human tumors." (PMID 35237846, 2022). "ICIs that are neutralizing antibodies against CTLA-4 and PD-1 can activate the anti-tumor immune response and inhibit the growth of tumor cells by blocking the negative inhibitory effect of PD-1 and CTLA-4 on T cells." (PMID 36110551, 2022). "The results confirmed that the tumor immunosuppressive environment of ESCC patients might be related to the relationship between LATS2 and PDL1 and CTLA4." (PMID 36118851, 2022). "CTLA-4 blockade induces expansion of the inducible T-cell costimulatory Th1-like CD4 effect or as well as exhausted-like TCD8+ cells, while PD-1 blockade primarily induces expansion of exhausted-like tumor infiltrating TCD8+ cells." (PMID 35774996, 2022). "In a mouse tumor model, fractionated radiotherapy and not single-dose RT induced an immune-mediated abscopal effect when combined with anti-CTLA-4 antibody." (PMID 35155221, 2022). "Anti-CTLA4 antibodies both block the interaction between CTLA4 and CD80/86, and can also deplete Tregs, thus facilitate the costimulation and expansion of tumor-specific CTL with improved clinical benefits." (PMID 35432319, 2022). "Therefore, we constructed a CTLA4-PD-L1-I chimeric protein (Protein vaccine) and evaluated its effect on TAA-induced iCCA tumor growth." (PMID 36341387, 2022). "It was shown that the treatment of tumor-bearing mice with anti-CTLA-4 antibody failed to induce tumor regression." (PMID 35681548, 2022). "CTLA-4, also known as CD152 (cluster of differentiation 152), is a transmembrane receptor constitutively expressed in regulatory T cells, which promotes immunosuppression in the tumor microenvironment." (PMID 35625837, 2022). "In addition, we deeply analyzed the potential value of this signature as a biomarker of tumor immunotherapy response and found that low-risk patients were more likely to benefit from postoperative chemotherapy, and they also might be benefit from ICI therapy based on anti-CTLA-4 or anti-TIM-3." (PMID 34497605, 2021). "This suggests that the tumor likely experiences increased infiltrates of clonal non-specific cells following anti-CTLA4 therapy." (PMID 33968757, 2021). "CTLA-4 expression in tumors was verified to be specific to T-cells and not the tumor cells using RT-PCR, indicating that the PET tracer signal from the tumor is specifically due to tumor-infiltrating T cells." (PMID 33391977, 2021). "Moreover, anti-CTLA-4 antibodies can increase the abundance of active CD8+ T cells by inhibiting the B7-CTLA-4 pathway and then promoting the infiltration of active CD8+ T cells into tumour tissue, thus enhancing the antitumour effect." (PMID 34419152, 2021). "Although remarkable progress has been made in cancer treatment by blocking CTLA-4 or PD-1 pathway with mAbs, most patients do not respond to therapy because of T cell-mediated primitive or acquired immune resistance to anti-tumor drugs." (PMID 34421887, 2021). "Therefore, we evaluated the relationship between the expression of immune inhibitory molecules (TIGIT, PDCD1LG2, PDCD1, LAG3, HAVCR2, CTLA4, and CD274) in the immune ignorant, immune inactive, and hot tumor subtypes." (PMID 33777927, 2021). "In addition, increased expression of the ligands for checkpoint inhibitors, such as PD1, CTLA4, TIM3, TIGIT, CD96, KLRG-1, and LAG3, on the tumor cells attenuates antitumor activity of NK cells." (PMID 34768814, 2021). "BEMPEG and anti-CTLA-4 treatments without local treatment did not improve survival, and these mice died due to primary tumor burden." (PMID 33937052, 2021).
tumor (continued). "Overexpression of CTLA4 and TIM3 in Treg cells and overexpression of LAG3 and TIM3 in tumor infiltrating T lymphocytes can prevent the activation of effector T cells, also resulting in immune escape of tumor cells." (PMID 34975896, 2021). "Also, among tumor-infiltrating CD8+ T cells, the proportion of PD-1+ cells and that of CTLA4+ cells were decreased by ZVI@CMC treatment." (PMID 34093872, 2021). "Mechanistically, this combination treatment with non-ablative radiation therapy and CTLA4 blockade led to increased density of tumor-infiltrating lymphocytes, increased CD8/CD4 ratio, and broadening of the TCR repertoire." (PMID 34733273, 2021). "The tumor cells with deactivated CD80 (TC-1/dCD80-1) were more immunogenic than parental cells and induced tumors that gained sensitivity to cytotoxic T-lymphocyte antigen 4 (CTLA-4) blockade, as compared with the TC-1 cells." (PMID 33923750, 2021). "More importantly, when combined with CTLA‐4 mAb therapy, Sunitinib showed the best tumor growth‐inhibitive effect without side effects." (PMID 33510997, 2021). "Mechanistically, CTLA-4 inhibition reduces CD4+ Treg proliferation and induces the expansion of a Th1-like CD4+ effector populations, while inhibiting PD-1 reduces T-cell exhaustion and increases CD8+ tumor infiltrating subsets." (PMID 34512641, 2021). "The therapeutic effect was associated with increased percentages of CD8+ T cells at the tumor site, indicating that other subsets of T cells, including CD4+ T cells and Tregs, may have limited roles during CTLA-4 blocking antibody cancer therapy." (PMID 33800368, 2021). "We analyzed tumor sections by quantitative multiplex immunofluorescence to characterize immune cell subsets in various tumor compartments in tumors without pretreatment and tumors exposed to preoperative anti-PD1/CTLA-4 checkpoint inhibitors (NABUCCO trial)." (PMID 34987518, 2021). "Increased TILs correlated with response to anti-PD-L1 and anti-CTLA-4 therapy, but PD-L1expression on tumor cells or PD-1 expression of T cells did not." (PMID 34353349, 2021). "Nonetheless, as in our model, a combination of prophylactic mRiok1 vaccination, anti-PD-1, and anti-CTLA-4 also failed to induce a protective anti-tumor response." (PMID 34771674, 2021). "The impact of CD80 expression on tumor cells on the efficacy of CTLA-4 blockade has not been sufficiently investigated yet." (PMID 33923750, 2021). "If any genes upregulated or downregulated in normal tissue Treg, non-tumor diseased Treg and tumor Treg are not collaborated with CTLA-4 regulation, they will be placed in non-collaboration gene groups." (PMID 34084175, 2021). "Immune checkpoints, such as cytotoxic T lymphocyte-associated antigen 4 (CTLA-4) and programmed cell death protein 1 (PD-1), transmit negative signals to CD8+ T-cell and reduce tumor-infiltrating lymphocytes during the anti-tumor process." (PMID 34207556, 2021). "There was a non-significant trend toward increased PB CX3CR1+ CD8+ T cells in B16 tumor-bearing mice without improvement of survival by combined CTLA-4/PD-L1 blockade therapy." (PMID 33658501, 2021). "CTLA-4 activation promotes the immunosuppression of CD8+ T cells and is influenced by other T-cell receptor pathways; antibody-mediated blockade has been shown to stimulate anti-tumor immune responses." (PMID 33918476, 2021). "Moreover, CDCA7 was significantly correlated with tumor-related immunosuppressive molecules including PDCD1, CD274, CTLA4, BTLA and LAG3." (PMID 33648519, 2021). "One of the mechanisms that tumor cells have adopted to evade immune responses takes advantage of the negative immune checkpoints—like CTLA-4—to induce T-cell anergy or dysfunction." (PMID 33996698, 2021). "In future studies it may be valuable to test this treatment approach in combination with inhibitors targeting these additional checkpoint ligands to further enhance the magnitude and/or duration of anti-tumor immunity stimulated by BEMPEG and anti-CTLA-4." (PMID 33937052, 2021).